ENSG00000269711 (novel protein)
Gene: Protein-coding gene on chromosome 19 (7,678,501 to 7,682,854, forward strand). Ensembl gene ENSG00000269711.
Genetic constraint (gnomAD): Loss-of-function variants: 12 observed, 12.84 expected, observed/expected ratio (o/e) 0.93, 90% interval 0.6 to 1.51. Missense variants: 213 observed, 166.27 expected, observed/expected ratio (o/e) 1.28, 90% interval 1.14 to 1.43. Synonymous variants: 77 observed, 64.98 expected, observed/expected ratio (o/e) 1.19, 90% interval 0.99 to 1.43.